INS (insulin)
Diseases named in the same sentence as INS in open-access papers (continued):
Sharing a sentence is not in itself a finding about the gene and the disease.
diabetes (continued). "There was evidence from multiple sources showing that elevated obesity measures were associated with each of elevated blood pressure; elevated glucose, insulin, or diabetes; and abnormal lipids." (PMID 35954531, 2022). "Insulin glargine is a long-acting insulin analog, which plays an important role in the treatment of diabetes mellitus." (PMID 36091767, 2022). "The students reported that their lowest level of knowledge was on how to administer insulin and on the proper diet for patients with diabetes and self-care management." (PMID 36675718, 2022). "Barriers to managing diabetes with insulin included fear/dislike of needles and injections (seven studies)." (PMID 35983585, 2022). "At present, conventional treatment strategies for diabetes should be decided and modified based on the severity of COVID-19 as patients treated with insulin have shown poorer outcomes than those under metformin treatment." (PMID 36425575, 2022). "It is the main downstream pathway of insulin action and the most important one among the various pathways in which insulin regulates glucose and lipid metabolism in diabetes." (PMID 35845783, 2022). "With financial pressure, some patients who need insulin to manage their diabetes have resorted to illegal activities such as borrowing insulin, importing insulin from lower-cost countries, or purchasing insulin from illegitimate internet pharmacies." (PMID 35156937, 2022). "The incidence of septic shock was 40.36% (2,867/7,104), insulin treatment was 54.43% (3,867/7,104), hypoglycemia was 14.26% (1,013/7,104), diabetes was 31.53% (2,240/7,104), and liver disease was 18.65% (1,325/7,104)." (PMID 35570924, 2022). "Despite 100 years of therapeutic development since the discovery of insulin, current diabetes therapies, such as continuous glucose monitors, insulin pumps and closed-loop systems, remain a treatment for the condition rather than a cure of the disease." (PMID 35288694, 2022). "Multiple mice and rat animal studies demonstrated that exercise exerts beneficial effects on diabetes by improving insulin secretion function, islet composition, beta-cell morphology, or glucose tolerance." (PMID 35742478, 2022). "Lactobacillus and Bifidobacterium species have been reported to improve glucose tolerance, glucose-induced insulin secretion, stabilized inflammatory activities, and decrease the frequency of diabetes." (PMID 35242140, 2022). "Prostate cancer: insulin-deprived environment in long-term diabetes results in a lower amount of insulin-like growth factor-1 receptor (IGF-1R), and higher plasma IGF-1 is associated with a higher risk of prostate cancer." (PMID 35207564, 2022). "There were 12 out of 14 questions where the participants with non-insulin use had more than 50% incorrect answers for total diabetes knowledge." (PMID 36527016, 2022). "I suppose the most obvious impact is there are days when I just can’t be bothered to take my medication, both the medication for the depression and the insulin for my diabetes and I know it’s stupid [...]." (PMID 35210344, 2022). "Examples of such interventions are aspirin for preeclampsia, progesterone for preterm birth, diet and insulin for diabetes, and growth assessment for stillbirth." (PMID 36360505, 2022). "SGLT2i is a newly developed drug used in the treatment of type 2 diabetes mellitus independent from insulin." (PMID 35476142, 2022). "Type 2 diabetes mellitus is a chronic metabolic disease characterized by resistance to peripheral insulin actions." (PMID 35083338, 2022). "Type-2 diabetes is the most common is usually in adults, which occurs when the body becomes resistant to insulin or doesn’t produce enough insulin by the pancreas and accounts for nearly 95% of all diabetes cases globally." (PMID 35427392, 2022). "Sacubitril/valsartan has previously been shown to reduce HbA1c levels and the need for insulin initiation in patients with HFrEF and diabetes in the PARADIGM-HF trial." (PMID 35717169, 2022).
diabetes (continued). "Overall, patients with T2DM had lower HRQoL than the general population, which was attributed to being older age, longer duration of diabetes, insulin use, obesity, inadequate glycemic control, and diabetes-related complications." (PMID 35180266, 2022). "After new diagnosis of T2D many patients are able to discontinue insulin therapy; however, there is a high rate of treatment failure requiring therapy intensification with restarting insulin or initiation of other diabetes medication." (PMID 36992756, 2022). "Merely giving information on management and pointing out the obvious like ‘you need to take care of your diabetes’ or ‘take insulin regularly’ was utterly ineffective." (PMID 38434003, 2022). "For patients with T1DM, intensive diabetes management with insulin therapy has been considered as the standard strategy for maintaining glycemic control near the normal range." (PMID 35707462, 2022). "The patient should be advised this is a ‘trial’ off insulin and if unsuccessful, insulin will need to be recommenced (particularly in older patients with long duration of diabetes)." (PMID 35445424, 2022). "Small-molecule drugs that inhibit the pancreatic KATP channel are widely used to boost insulin secretion for the treatment of diabetes and are therefore named insulin secretagogues (ISs)." (PMID 35847046, 2022). "Using hyperinsulinemic-euglycemic clamp as a validation criterion, investigators established an estimated glucose disposal rate (eGDR) to enable the evaluation of insulin sensitivity in type 1 diabetes mellitus (T1DM)." (PMID 36452320, 2022). "By multivariate regression, birth weight was the strongest predictor of cord blood leptin (P<0.001), while maternal diabetes and BMI were the strongest predictors of cord blood insulin (both P<0.001)." (PMID 35197933, 2022). "The injection (insulin) is fine and very effective to control the disease (diabetes); nothing strange with it." (PMID 35854336, 2022). "Although most diabetes cases eventually need insulin therapy, the initiation of insulin is often delayed." (PMID 36467033, 2022). "Both in diabetes and heart failure, there is an elevation of insulin levels, which constantly stimulates IRs." (PMID 35454166, 2022). "Since differentially methylated insulin gene is recently detected as biomarker of progressive beta cell loss, the discovery of novel blood-based epigenetic biomarkers may be used to predict risk for diabetes development and development of its related complications." (PMID 36246880, 2022). "Duration of diabetes ≥ 10 year, BMI < 18.5 kg/m2, SDBG ≥ 3.0 mmol/L, and subcutaneous injection of insulin as preoperative hypoglycemic regimen were the main risk factors for perioperative hypoglycemia." (PMID 35538461, 2022). "A total of 78.24% and 34.71% of diabetes-treated patients were on oral antidiabetic medications or injected insulin, 85.77% were on diet control, and 78.24% were monitoring blood sugar." (PMID 35457673, 2022). "The pharmacological agents, used currently for the treatment of diabetes mellitus include mainly oral anti-diabetic drugs as well as insulin subcutaneous therapy." (PMID 36544524, 2022). "While the mode of action and courses of treatment for all forms of diabetes are distinct, the diseases all eventually result in the dysfunction and/or death of the pancreatic β cell - the body’s source of insulin." (PMID 36339450, 2022). "Some macroelements such as Mg and Fe and certain trace elements such as B, Cr, Cu, Zn, and Cd enhance insulin action by activating insulin receptor sites, thus playing a specific role in the pathogenesis of diabetes and dyslipidemia." (PMID 35310037, 2022). "The main pathogenesis of diabetes is the inability of β-cells to secrete insulin required for metabolism, resulting in an imbalance in blood glucose homeostasis." (PMID 36407115, 2022). "Closed-loop (artificial pancreas) systems for automated insulin delivery have been likened to the holy grail of diabetes management." (PMID 35733769, 2022).
diabetes (continued). "(c) In uncontrolled subjects with diabetes treated with insulin, 3 vs 6 meals per day resulted in decreased body weight, HbA1c, total daily insulin requirements and higher expression of clock genes." (PMID 35215472, 2022). "And supported by an AUC of 0.842 (sensitivity: 72.1%, specificity: 84.0%) and a kappa value of 0.552, the added value of DFF in diabetes classification was further validated in identifying both insulin-dependent LADA and T2DM patients in our study population." (PMID 36204110, 2022). "After analyzing all of the findings regarding the consequences of insulin analogs, it became clear that recombinant insulin has a critical role in the treatment of diabetes." (PMID 35723344, 2022). "We conclude that the synthesized nanoparticles are more powerful in reducing the hyperglycemia and enhances the IRS1 and AMPK expression for treatment of diabetes, which aid in glucose uptake and insulin sensitization." (PMID 35956652, 2022). "Early into this post-insulin era, it was recognised that diabetes is a chronic illness and that treatment would involve the lifelong combination of insulin regimens with diet, exercise and infection protocols." (PMID 35994083, 2022). "Treatment barriers include, for example, feeling pain when getting a finger prick or taking an insulin shot, feeling embarrassed about treatment, arguing with parents, or difficulty in caring for their diabetes." (PMID 36620301, 2022). "PID control has been successfully applied in other drug delivery applications, such as automated insulin delivery for glycemic control in diabetes Steil (2013)." (PMID 36338121, 2022). "Females, those in younger age groups, patients of Malay and Indian ethnicity, those with shorter diabetes duration, overweight patients, patients with dyslipidemia, and insulin users had higher LDL-C trends than their respective counterparts." (PMID 36317122, 2022). "Polysaccharides isolated from Vigna angularis and mulberry leaf alleviated diabetes in diabetic rats by activating the signaling pathway of insulin/PI3K/AKT or blocking islet cell apoptosis." (PMID 35845787, 2022). "The intervention of insulin in the regulation of renal sodium balance is altered in experimental models of diabetes." (PMID 36289636, 2022). "In normoglycemic non-obese youth, peak insulin concentrations occur at 30 min post drink, while the insulin peak is at 120 min in adolescents with prediabetes and diabetes." (PMID 35991189, 2022). "If any effect on insulin signaling, the mutant actually improves insulin sensitivity in mice with advanced diabetes." (PMID 36337049, 2022). "Type 2 diabetes mellitus, however, is a manifestation of IR (insulin resistance), a defective response to insulin and a subsequent altered glucose metabolism." (PMID 36361633, 2022). "In diabetes, lipoprotein lipase activity is inhibited due to insulin insufficiency, which promotes hypertriglyceridemia." (PMID 35345832, 2022). "Average age at diagnosis of diabetes of the participants 43.8 ± 11.4 years and the duration of diabetes was 7.2 ± 6.0 years and 44.7% patients were on insulin treatment." (PMID 35022493, 2022). "Diet-induced diabetes was verified by increased serum insulin, fasting blood glucose, and impaired glucose tolerance." (PMID 35281739, 2022). "Over the last few decades, there have been a plethora of studies that have investigated diabetes therapeutics, including insulin, to attenuate AD pathology and improve cognitive function." (PMID 36555450, 2022). "PPARγ is a target for insulin sensitizing drugs such as glitazones, which improve plasma glucose maintenance in patients with diabetes." (PMID 36558918, 2022). "In conclusion, the present study clearly demonstrates that XAF1 expression in pancreatic β-cells via HFD-induced secretion of IFNβ from macrophages promoted β-cell apoptosis, thereby leading to a reduction in insulin secretion and exacerbation of diabetes." (PMID 35829914, 2022).
diabetes (continued). "This prompted extensive research into insulin action and resistance (IR), resulting in the universally agreed fact that IR is a core finding in patients with type 2 diabetes mellitus (T2DM)." (PMID 35323652, 2022). "Pathological section, mast cell staining analysis, glucose and insulin tolerance test, ELISA, real-time PCR, and Western blot helped to explore the potential mechanisms by which food allergy promotes diabetes." (PMID 36496564, 2022). "Diabetes mellitus (DM) is a common metabolic disorder characterized by high plasma glucose over a long period due to defects in insulin synthesis, insulin receptor, or postreceptor signaling pathway events." (PMID 35186807, 2022). "In terms of insulin, diabetes patients used premixed insulin more often with a proportion of 53.8% in the nonrespiratory series and 59.9% in the respiratory group in 2018." (PMID 36093107, 2022). "We investigated the effect of spermidine on diabetes incidence, pancreatic inflammation, insulin granule homeostasis, pancreatic autophagy levels, and immune cell pool." (PMID 35296698, 2022). "Most of the current drug-therapy glucose-lowering mechanisms for diabetes include targeting pancreatic β-cells, reducing pancreatic β-cell apoptosis, promoting β-cell proliferation and regeneration, and promoting insulin secretion." (PMID 35164115, 2022). "During the development of diabetes, an increase in H2S can inhibit the secretion of insulin and reduce the overload of islet cells." (PMID 35743160, 2022). "Diabetes mellitus is a group of metabolic diseases characterized by abnormal insulin secretion, insulin action, or both situations leading to hyperglycemia." (PMID 35464780, 2022). "Physical activity has long been prescribed to patients with diabetes due to improvements in blood glycaemia levels and insulin sensitivity." (PMID 34979996, 2022). "For example, they discussed the advantages of HE and PA on their general diabetes control, such as achieving good glycemic control, and being able to decrease insulin doses [Quote #13]." (PMID 35793375, 2022). "Overall, these findings suggest that 2 years of diabetes management were effective in improving adipose tissue, sTREM2 levels, and insulin resistance, thereby exhibiting potential preventive effects on cognitive impairment in the HbA1c-decreased group." (PMID 35592778, 2022). "All 30 participants reported that insulin pump therapy benefited their diabetes self-management around exercise; benefits noted were flexibility of insulin dosing, no injections, convenience, and the options to adjust or suspend basal insulin." (PMID 35233639, 2022). "Type 1 diabetes mellitus is an autoimmune illness typified by the demolition of pancreatic β-cells followed by dreadful insulin scarcity." (PMID 35282429, 2022). "The AKT2 is the most abundant AKT isoform in human insulin-sensitive cells and plays a pivotal role in insulin’s metabolic response, especially in type 2 diabetes mellitus and insulin resistance." (PMID 35906673, 2022). "In terms of diabetes medications, participants endorsed adherence, reporting taking oral medications and insulin as prescribed." (PMID 36221145, 2022). "Collectively, it suggests that IL-18 plays a role in glucose homeostasis, insulin secretion, and the development of diabetes." (PMID 36547931, 2022). "In other words, the paramount role of insulin during fetal development is highlighted by the macrosomia of newborns born to mothers with pre-existing diabetes, where maternal hyperglycemia drives overproduction of insulin by the fetal pancreatic beta cells." (PMID 36440208, 2022). "Glycemic control is crucial for diabetic patients, particularly those on insulin, since it helps prevent diabetes-related complications." (PMID 35573427, 2022). "Our results demonstrate a prominent role for insulin secretion defects in the pathophysiology of diabetes in this group." (PMID 34689214, 2022).
diabetes (continued). "Adenosine signalling has a crucial role in diabetes mellitus pathophysiology due to its modulation of insulin secretion and regulation of β-cell homeostasis." (PMID 35663309, 2022). "Until the end of 2004, individuals attending the John Hunter Children's Hospital (JHCH) paediatric diabetes clinic were mostly using conventional twice daily insulin injections." (PMID 35715954, 2022). "Human pluripotent stem cells have the potential to provide an unlimited supply of insulin-producing β cells for treating patients with diabetes (T1D, T2D, MODY, monogeneic diabetes)." (PMID 36545154, 2022). "Without detailed knowledge of the treatment given to subjects with diabetes and the blood glucose levels of the subjects in the different groups, the HbA1c results are unreliable as a marker of insulin sensitivity." (PMID 35205269, 2022). "Diabetes mellitus (DM) can be described as a group of metabolic diseases indicated by chronic hyperglycemia resulting from impaired insulin secretion, action or both." (PMID 35742719, 2022). "As insulin continues to be major therapeuticfor treating diabetes,and diabetes is increasing worldwide, the need for new stabilizingexcipients for the peptide continues to increase." (PMID 35968684, 2022). "PPARγ agonists are already being used in the treatment of conditions such as diabetes, where they act as insulin sensitizers." (PMID 36591308, 2022). "Patients with diabetes mellitus type 1 depend on exogenous insulin to keep their blood glucose concentrations within the desired range." (PMID 36213069, 2022). "The majority of diabetic patients are diagnosed with type 2 diabetes mellitus, which can be divided into two major pathologies: insulin resistance, in which insulin becomes less effective, and decreased insulin secretion from pancreatic β-cells." (PMID 35625542, 2022). "Insulin is used in approximately one-third of patients with diabetes, and it has emerged as an independent risk factor for left ventricular dysfunction and heart failure hospitalizations." (PMID 35574440, 2022). "Insulin is administered with the help of the InsuJetTM system, which was created for people with diabetes." (PMID 36381916, 2022). "Attenuates the decline in muscle mass and insulin sensitivity that occurs with increasing age and diabetes." (PMID 35831938, 2022). "The transition to green nutrition improves the functionality of the pancreatic beta cells, the production of gastrointestinal incretins and the excretion and sensitivity to insulin, all of which results in greater control of diabetes." (PMID 36142725, 2022). "The management of diabetes mellitus in an insulin-dependent patient is challenging in the setting of concomitant antibody-mediated-insulin hypersensitivity." (PMID 35350098, 2022). "Diabetes Mellitus (DM) is a common metabolic disease, characterizing by the hyperglycemia that impairs insulin production in the body." (PMID 35606520, 2022). "A few of the interviewed school nurses, especially those from smaller municipalities, were more involved in diabetes management, for example, by teaching and supporting schoolteachers or helping the child with insulin injections." (PMID 36011214, 2022). "Diabetes mellitus (DM) refers to a group of metabolic disorders, characterized by hyperglycemia resulting from impaired insulin secretion or action." (PMID 35207724, 2022). "The findings will help design patient-centered interventions to promote adherence to insulin in this age group, guide patients’ consultations and diabetes self-management education (DSME) programs." (PMID 35673417, 2022). "Diabetes mellitus (DM) is a category of metabolic illnesses defined by chronic hyperglycemia resulting from an absolute or relative insulin shortage and insulin resistance (IR)." (PMID 36362461, 2022).